HOTAIR (HOX transcript antisense RNA)
Diseases named in the same sentence as HOTAIR in open-access papers (continued):
Sharing a sentence is not in itself a finding about the gene and the disease.
cancer (705 papers, 2011 to 2026). A tumor composed of atypical neoplastic, often pleomorphic cells that invade other tissues. "We therefore conducted an updated meta-analysis to accurately assess the association of the HOTAIR rs920778 polymorphism with cancer risk." (PMID 40642606, 2025). "The rs920778 polymorphism has a genotype-specific effect on HOTAIR expression, resulting in higher HOTAIR expression in T allele carriers, which affects susceptibility to cancer." (PMID 40642606, 2025). "LncRNA HOX transcript antisense intergenic RNA (HOTAIR) has been implicated in the pathogenesis of many cancers, and developing small-molecule inhibitors targeting HOTAIR remains a key clinical challenge." (PMID 40042761, 2025). "The impact of the HOTAIR rs7958904 polymorphism on cancer risk appears to be strongly dependent on cancer type." (PMID 41463069, 2025). "Another lncRNA called HOTAIR linked with the invasion of the muscle layer of the uterus and migration of cancer cells to the lymph nodes in EC." (PMID 39912983, 2025). "Scientists have discovered that long ncRNAs MALAT1 and HOTAIR demonstrate substantial value for liquid biopsy exams as cancer diagnostic and prognostic indicators across numerous cancer types." (PMID 40959208, 2025). "The lncRNA HOTAIR, implicated in various cancers including OSCC, suppresses the expression of downstream tumor suppressor genes by recruiting EZH2 and mediating H3K27 trimethylation." (PMID 41221298, 2025). "We therefore pooled 29 studies to assess the association of HOTAIR rs920778 polymorphisms with cancer susceptibility." (PMID 40642606, 2025). "Overexpression of HOTAIR, a well-known oncogenic lncRNA, has been linked to aggressive features of various cancers, including poor differentiation, in various cancers." (PMID 40072110, 2025). "As an oncogene, HOTAIR is expressed in a variety of human cancers, and its overexpression is associated with the proliferation, invasion, progression, and metastasis of cancer cells, as well as a low survival rate." (PMID 40642606, 2025). "HOTAIR is one of the cancer-associated lncRNAs, many studies have shown that it is overexpressed in various solid tumors, in cancer initiation, progression, angiogenesis, and metastasis." (PMID 40686703, 2025). "For example, elevated levels of HOTAIR in cancer cells are associated with poor prognosis and aggressive tumor stages." (PMID 41361062, 2025). "This ability to reprogram chromatin was quickly linked to cancer, and today, HOTAIR is recognized as relevant in various tumor types." (PMID 38275875, 2024). "HOTAIR has been implicated in regulating autophagy, influencing both cisplatin resistance and sensitivity to radiotherapy in various cancers." (PMID 39684286, 2024). "HOTAIR, an lncRNA exhibiting aberrant expression across various cancers, has been particularly implicated in TNBC due to its high expression levels." (PMID 39286016, 2024). "Studies have also implicated HOTAIR signalling as a major molecular agent conferring chemoresistance to cancer cells against multiple chemotherapeutics." (PMID 38682637, 2024). "The overexpression of HOTAIR in cancer epithelial cells was discovered to cause histone methylation and cancer invasion." (PMID 38294554, 2024). "Enrichment analyses focusing on cancer signaling pathways and transcription factors demonstrated a significant association of HOTAIR with the transcriptional regulation of both pathways." (PMID 39273054, 2024). "Notable lncRNAs implicated in the advancement of cancer include HOX Transcript Antisense RNA (HOTAIR) and metastasis-associated lung adenocarcinoma transcript 1 (MALAT1)." (PMID 39483548, 2024). "For instance, HOTAIR’s involvement in modulating chromatin states and influencing gene expression linked to cancer aggressiveness has been extensively documented, suggesting its potential as a biomarker." (PMID 39512820, 2024).
cancer (continued). "Accumulating research is drawing attention to correlation between HOTAIR’s SNPs and the risk for various cancer types but the results obtained so far have been equivocal." (PMID 38339289, 2024). "A growing number of investigations are drawing attention to the relationship between HOTAIR’s SNPs and the risk of various cancer types but the results obtained so far have been equivocal." (PMID 38300349, 2024). "Some reports indicate that polymorphisms of the HOTAIR gene are associated with a variety of cancers, including breast, pancreatic, gastric, thyroid, and colorectal cancers." (PMID 38587571, 2024). "The dysregulation of HOTAIR was implicated in the malignant progression and drug resistance development in cancers, including lung cancer, breast cancer and CRC." (PMID 39055884, 2024). "For instance, miR-34a, a well-studied tumor suppressor, has shown therapeutic potential in various cancers, LncRNAs, such as HOTAIR and MALAT1, are associated with cancer progression and metastasis." (PMID 39415281, 2024). "It is worth noting that the HOTAIR enhancer contains a single nucleotide polymorphism, rs920778T, which is associated with HOTAIR overexpression and increased susceptibility to cancer." (PMID 38434620, 2024). "The interplay of HOTAIR and miR‐214‐3p has been implicated in the regulation of cancer cell proliferation and invasion." (PMID 39347925, 2024). "The results show that HOTAIR is highly expressed in most tumors indicating that HOTAIR is linked to cancer development and prognosis." (PMID 38696320, 2024). "Among these, the lncRNA homeobox transcript antisense intergenic RNA (HOTAIR), widely implicated in cancer initiation and progression, likewise plays a significant role in anticancer drug resistance." (PMID 38887279, 2024). "The expression of HOTAIR has been reported to be elevated in various cancers, and its overexpression is associated with tumor growth, invasion, and metastasis." (PMID 39156986, 2024). "These Authors demonstrated that the cytokine, mainly secreted by cancer-associated fibroblasts (CAFs) in tumor microenvironment and acting in a paracrine manner, activates HOTAIR gene expression." (PMID 37308974, 2023). "HOTAIR is most enriched in the ‘cell cycle’ pathway and pathways relating to infections, namely ‘herpes simplex virus 1 infection’ and ‘complement and coagulation cascades’, which are associated with key functions of HOTAIR in cancer." (PMID 36924407, 2023). "To date, HOTAIR has been reported to be abnormally upregulated in at least 24 types of cancers, many of which are associated with metastasis and poor prognosis via chromatin regulation and R-loops." (PMID 36750826, 2023). "HOTAIR has also been associated with a wide range of cancers and has shown to have oncogenic properties when overexpressed." (PMID 36869839, 2023). "One specific lncRNA, HOX transcript antisense intergenic RNA (HOTAIR), has been shown to be upregulated in many cancers and linked to metastasis, aggressiveness, and poor patient prognosis." (PMID 37384249, 2023). "HOTAIR is also associated with the epigenetic regulation, cancer susceptibility, poor survival, tumor recurrence, immune escape, and oncogenic signaling pathways." (PMID 36997931, 2023). "As a master regulator of cancer, HOTAIR is associated with various cellular and molecular mechanisms involved in carcinogenesis and cancer progression." (PMID 36997931, 2023). "First, studies on gastrointestinal tumors suggest that HOTAIR is vital for cancer cell survival and deficiency of HOTAIR leads to cancer cell apoptosis." (PMID 36924407, 2023). "Specifically, they found the SNP rs920778 in the intron 2 of HOTAIR gene significantly associated with increased risk of carcinoma occurrence." (PMID 37308974, 2023). "Dysregulations of LncRNA HOTAIR were often involved in the occurrence and development of malignant tumors and were associated with tumor invasion, progression, and metastasis." (PMID 36338672, 2022).
cancer (continued). "Further, a strong association between lncRNAs and human cancer was established as many lncRNAs, including HOTAIR and MALAT, were found dysregulated in various cancers." (PMID 36124026, 2022). "HOTAIR is well known for occurring alongside cancer, and its polymorphisms are also known as various diseases; selected polymorphisms (rs920778, rs1899663, rs4709314, and rs12826786) are especially associated and reported with certain diseases." (PMID 36421813, 2022). "Our results demonstrate that HOTAIR from both human and mouse species plays a pivotal role in cancer cachexia associated with cisplatin chemotherapy, suggesting that they share similar biological functions." (PMID 36471329, 2022). "HOX transcript antisense RNA (HOTAIR) is an lncRNA product of HOXC that has been implicated in invasion and progression of various cancers, with high levels of HOTAIR reported in papillary thyroid carcinoma and epithelial ovarian cancer." (PMID 36421813, 2022). "LncRNA HOX Transcript Antisense Intergenic RNA (HOTAIR) promotes tumor progression and increases cancer susceptibility by regulating microRNA expression and function." (PMID 35619625, 2022). "Overexpression of HOTAIR has been associated with a metastasis-promoting phenotype in various cancers." (PMID 35087108, 2022). "Briefly, aberrant expression of HOTAIR is frequently associated with pathogenesis and mostly with metastatic progression of several human cancers." (PMID 35359879, 2022). "Different polymorphisms, particularly present in intronic sequences and promoter regions of HOTAIR, are often associated with its aberrant expression, patient prognosis, and cancer susceptibility in different tumor phenotypes." (PMID 35359879, 2022). "HOTAIR is a long noncoding RNA (lncRNA) which serves as an important factor regulating diverse processes linked with cancer development." (PMID 34266873, 2021). "A recent study extensively investigated the association of HOTAIR polymorphisms with different cancer risks." (PMID 34199840, 2021). "Ectopic HOTAIR expression has been implicated in a variety of cancers, such as pancreatic, colorectal and non-small-cell lung cancers." (PMID 34527584, 2021). "Even though the mechanism of its action needs further research to prove, we already know that HOTAIR polymorphisms were associated with cancer risk and the toxicity of cisplatin-based chemotherapy." (PMID 34199840, 2021). "Recently, lncRNAs including PVT1, LINC00963, and HOTAIR have been reported to be associated with radioresistance in many types of cancers." (PMID 33573349, 2021). "In breast cancer, the interaction of HOTAIR with the Polycomb Repressive Complex 2 results in changes in histone methylation and gene expression associated with an increase in cancer cell metastasis." (PMID 33499210, 2021). "HOX Transcript Antisense RNA (HOTAIR) is a 2,148-nt lncRNA that has been associated with cancer and which is encoded within the Homeobox C (HOXC) gene cluster of chromosome 12." (PMID 34266873, 2021). "HOTAIR is a lncRNA implicated in the pathogenesis of several diseases, including cardiovascular diseases and cancers." (PMID 33733597, 2021). "Recently, the level of HOTAIR has been found to be associated with survival in several types of cancer." (PMID 34367966, 2021). "HOTAIR gene contains a functioning single nucleotide polymorphic site rs12826786 C>T that has been associated with several cancer types." (PMID 33584136, 2021). "Several epidemiological investigations demonstrate an association between HOTAIR polymorphisms and cancers however, the findings were inconsistent and controversial." (PMID 34582651, 2021). "There are several well-established lncRNAs that have been linked to cancers (e.g., HOTAIR, H19, MEG3, MALAT1)." (PMID 33803619, 2021). "The results of this study showed that HOTAIR is not only associated with the development of cancer but also with pregnancy-associated diseases." (PMID 33809601, 2021).
cancer (continued). "It has become increasingly obvious that HOTAIR dysregulation in several types of cancer is closely associated with the proliferation, metastasis, and invasion of tumor cells." (PMID 34367966, 2021). "Several studies reported that different polymorphisms, especially in intronic sequences as well as in promoter regions of HOTAIR, are often associated with its aberrant expression, patient prognosis and cancer susceptibility in different tumor types." (PMID 34576322, 2021). "The single nucleotide polymorphism rs920778 T located in the HOTAIR enhancer has shown to be associated with elevated expression of HOTAIR and with cancer susceptibility." (PMID 32154165, 2020). "Aberrant expression of HOTAIR was associated with cancer development, progression, and drug resistance in different cancers." (PMID 31974341, 2020). "As a result, HOTAIR has emerged as a promising diagnostic and prognostic biomarker for multiple cancer types." (PMID 32785167, 2020). "Recent studies suggested that SNPs of HOTAIR (such as rs920778, rs4759314, rs1899663, rs12826786, rs874945, rs7958904, and rs10783618) acted as potential cancer susceptibility loci and were significantly associated with the increased risk of various cancers." (PMID 32117729, 2020). "Much evidence suggests that misregulation of HOTAIR is associated with a variety of cancers and cancer metastasis." (PMID 32650720, 2020). "The downregulation of miR-7 in BC patients is strongly associated with BC cancer stem cells and correlates with HOTAIR expression." (PMID 32397382, 2020). "Overexpression of HOTAIR has been associated with poor prognosis, invasiveness and aggressiveness of various cancer types." (PMID 32650779, 2020). "The multifunctional HOTAIR is implicated in the different aspects of cancer pathophysiology by regulating gene expression at the transcriptional, post-transcriptional, and epigenetic level." (PMID 31195674, 2019). "Significant associations between overexpression of HOTAIR and susceptibility, metastasis and/or poor prognosis of several human cancers such as liver, breast, pancreas, colon, lung, laryngeal, nasopharyngeal, and esophageal cancers have been reported." (PMID 30867650, 2019). "Aberrant HOTAIR expression has been detected in several human cancers associating its role with tumor proliferation, angiogenesis, progression, drug resistance and worse prognosis." (PMID 31137568, 2019). "Current evidences have revealed the association of HOTAIR with progression, in addition to the prediction/prognosis of many different cancer types (including glioblastoma, liver, gastric, pancreatic, colorectal and cervical malignancies)." (PMID 31796041, 2019). "Cancer stem cells from breast, oral and colon carcinomas, and gliomas express high levels of HOTAIR associated with increased stemness and metastatic potential." (PMID 30654440, 2019). "Recently, some studies indicating the potential role of SNPs of HOTAIR in cancer susceptibility have been published." (PMID 30873206, 2019). "To further the clinical relevance of our work and HOTAIR importance, we explored the possibility for any association of the HOTAIR expression to overall cancer survival." (PMID 31195674, 2019). "Polymorphism rs920788 was also located on the intron of HOTAIR gene and was proved to be able to enhance the intronic enhancer activity and increase HOTAIR expression in several cancer cells." (PMID 29423075, 2018). "Recently, several lines of published studies have researched the associations of HOTAIR polymorphisms with different cancers susceptibility, whereas their conclusions are discordant." (PMID 29463216, 2018). "HOTAIR (Hox transcript antisense RNA) is an lncRNA known to be involved in development, cancer and high risk metastases, at least partly through interaction with PRC2 and regulation of HOX genes." (PMID 30567492, 2018).
cancer (continued). "To further elucidate the mechanisms underlying CAF-induced HOTAIR activation, we used ChIP technology to identify the genomic locations bound by SMADs in cancer cells before and after co-culture with CAF-CM." (PMID 29325547, 2018). "We conducted an up-to-date meta-analysis to pool eligible studies and to further explore the possible relationships between HOTAIR polymorphisms (rs920778, rs7958904, rs12826786, 4,759,314, rs874945, and rs1899663) and cancer risk." (PMID 29463216, 2018). "HOTAIR is one of the first lincRNAs to be reported and associated with the development of cancer and also the first lincRNA to regulate genes at a distance." (PMID 29732012, 2018). "Several lncRNAs reportedly having crucial roles in cancer, including HOTAIR, MALAT1 and H19, have been reported to be linked to survival." (PMID 30038703, 2018). "For example, the down-regulation of HOTAIR is associated with cancer progression in 26 human tumor types." (PMID 30128179, 2018). "HOTAIR has also been shown to have functional roles in a variety of human cancers, being associated with patients’ decreased OS, increased metastatic potential, tumor recurrence and chemotherapy resistance." (PMID 29644006, 2018). "Other lncRNAs such as ANRIL (CDKN2B antisense RNA 1), HOTAIR, and GClnc1 (gastric cancer-associated lncRNA 1) also function as scaffolds to regulate gene expression." (PMID 29416704, 2018). "Among the extensively studied lncRNAs, HOTAIR was found to be associated with the mechanism of radiosensitivity in several cancers." (PMID 30355300, 2018). "Several research groups have reported HOTAIR association in different cancers evolutionary processes including, EMT, TNM, prognosis, drug resistance, metastasis, DFS, OS, and tumor development." (PMID 30693021, 2018). "HOTAIR overexpression correlates with many cancers and it is linked to cancer cell resistance to cisplatin." (PMID 29156779, 2017). "Previously, four papers have discussed the association of HOTAIR polymorphisms with cancer risk by meta-analysis." (PMID 27965458, 2017). "Previous studies have investigated the potential association between HOTAIR polymorphisms and cancer risk in Chinese population." (PMID 28938673, 2017). "A significant association between HOTAIR rs4759314 polymorphism and cancer risk was observed in dominant and heterozygous models for Chinese." (PMID 28938673, 2017). "A number of studies show that increased expression of HOTAIR enhances cell proliferation and invasion of cancer cells and has been associated with tumour progression and prognosis." (PMID 29138748, 2017). "The results revealed that elevated HOTAIR expression was associated with poor prognosis in cancer patients (HR = 2.16, 95% CI = 1.73–2.69, P < .001)." (PMID 28591050, 2017). "Herein, we conducted a meta-analysis to summarize all eligible case-control studies to evaluate the overall cancer risk and common lncRNAs (HOTAIR, PRNCR1, H19, and POLR2E) polymorphisms." (PMID 28159929, 2017). "Odds ratios with 95% confidence intervals were applied to assess the association between rs920778, rs4759314, rs7958904, rs874945 and rs1899663 polymorphisms of HOTAIR and cancer susceptibility." (PMID 28938673, 2017). "For clinical tumor stage, high levels of HOTAIR were associated with advanced clinical stage in all cancer types in this study." (PMID 28591050, 2017). "At present, HOTAIR polymorphisms are the most commonly studied than other lncRNAs in human diseases, particularly in cancer." (PMID 28159929, 2017). "Recently, the association between lncRNA HOTAIR polymorphisms and cancer risk has been developed gradually." (PMID 28938673, 2017). "A total of 26 articles on relationship between HOTAIR SNPs and cancer risk were retrieved after first search in PubMed, Embase and Web of Science." (PMID 27965458, 2017).